MGMT (O-6-methylguanine-DNA methyltransferase)
Diseases named in the same sentence as MGMT in open-access papers (continued):
Sharing a sentence is not in itself a finding about the gene and the disease.
glioma (continued). "In this study, we also found that signature 3 was linked to 7+/10−, signature 13 was linked to ATRX mutation and MGMT promoter methylation, and signature 16 was linked to grade in glioma." (PMID 34307451, 2021). "In terms of ME of tumors, the present study determined that ME was heterogeneously distributed in different glioma individuals, which is related to tumor grade and MGMT methylation, IDH mutation, and 1p/19q co-deletion status." (PMID 34784919, 2021). "Next, it is interesting to identify the differentially expressed genes between IDH mutant and IDH wild type glioma patients or identify the genes most associated with MGMT methylation and EMP3 expression." (PMID 34335936, 2021). "In recent years, the identification of molecular alterations (including IDH, TERT promoter mutation, MGMT methylation, and 1p/19q codeletion) associated with the prognosis of glioma." (PMID 33777772, 2021). "Consistently, this cluster also exhibited a higher percentage of IDH mutation, 1p/19q codeletion and MGMT-promoter methylation, which were all reported being associated with a favor prognosis in glioma." (PMID 34307451, 2021). "Knocking down MGMT expression in-vitro demonstrated increased susceptibility of glioma cells to TMZ treatment." (PMID 33500708, 2021). "There is increasing evidence, that the minor T allele of SNP rs16906252 is associated with MGMT promoter methylation and/or longer overall survival in colon cancer, glioma, lung cancer, and oral lichen planus." (PMID 34830407, 2021). "There have been many studies on the association between MGMT promoter CpG sites and glioma-related candidate SNPs." (PMID 33588926, 2021). "Consistently, our data demonstrated that rs11016798 TT genotype associated with higher MGMT expression decreased the risk of developing glioma." (PMID 34544433, 2021). "Among these molecular markers, IDH1, 1p19q, and MGMT methylation have been closely associated with the prognosis and chemotherapy sensitivity of glioma patients, although these markers have limited sensitivity and accuracy." (PMID 34876094, 2021). "Logically, rs10659396 del allele associated with higher MGMT expression was found to decrease the risk of developing glioma." (PMID 34544433, 2021). "The study demonstrates that an insertion variant of MGMT rs10659396 confers susceptibility to glioma by downregulating MGMT expression through disrupting a STAT1 binding site." (PMID 34544433, 2021). "Recently, O6-methylguanine-DNA methyltransferase (MGMT) promoter methylation is implicated in drug resistance of TMZ against glioma." (PMID 34739394, 2021). "Even many molecular characteristics of gliomas such as the combined deletion of 1p/19q, IDH1 mutations, and hypermethylation of the MGMT promoter are expected to be detected in circulating tumor cells in peripheral serum of glioma patients." (PMID 33777749, 2021). "The demethylating enzyme MGMT acts directly in repairing O6-methylguanine, consequently avoiding gene mutation and glioma cell death." (PMID 33803885, 2021). "The epigenetic silencing of the MGMT gene by promoter hypermethylation leads to loss of MGMT protein expression thus limiting the activity of glioma repair function." (PMID 33282092, 2020). "Overall, this cohort was representative of unmethylated MGMT and lower-grade gliomas, which had a higher risk of being upgraded to sGBM." (PMID 33392065, 2020). "Methylation of the promotor region of the O6-methylguanine-DNA-methyltransferase (MGMT) gene is another molecular marker which is associated with more favorable outcome in glioma WHO grade III and IV3,4." (PMID 33184319, 2020). "In glioma with IDH mutation, a higher rate of O6-Methylguanine-DNA-Methyltransferase (MGMT) promotor methylation was detected than in IDHwt glioma." (PMID 33212941, 2020). "With that in mind, we evaluated for the first time the degree of resistance to TMZ treatment in 18 patient-derived glioma cells and its association with MGMT and MPG mRNA levels." (PMID 33335215, 2020).
glioma (continued). "the objective was to evaluate the impact of IDH1 R132H mutation, MGMT methylation and PD-L1 expression in high grade glioma that received standard therapy (surgery, radiation and chemotherapy) to overall survival (OS)." (PMID 33282092, 2020). "In contrast, in MGMT-unmeth gliomas, TERT promoter mutation was regarded as an indicator of poor prognosis." (PMID 32957941, 2020). "On the other hand, TERT promoter mutation was an indicator of worse outcome in MGMT-unmethylated (MGMT-unmeth) gliomas (HR = 1.86; 95% CI = 1.54–2.26; p-value < 0.001)." (PMID 32957941, 2020). "For the grade IV glioma group, Indians were found to have the highest incidence of positive results for two of the biomarkers: MGMT promoter methylation (50%) and IDH1 mutation (30%)." (PMID 32005184, 2020). "IDH1/2 mutations proved independent prognostic factors in glioma and associated with MGMT methylation for better survival." (PMID 33552543, 2020). "The methylation of MGMT promoter is linked to a favorable prognosis in glioma treated by TMZ since MGMT expression is decreased, which leads to impaired DNA repair ability in tumor cells and enhances the sensitivity to alkylating agents." (PMID 33266110, 2020). "Highest yield for screening includes recurrent post-TMZ gliomas with MGMT promoter methylation and/or IDH1 mutations." (PMID 32051040, 2020). "This is noteworthy because tumor-associated astrocyte-derived EVs contain O6-methylguanine-DNA methyltransferase (MGMT) mRNA which promotes anti-tumor resistance in glioma cells." (PMID 33178687, 2020). "IDH mutation, MGMT promoter methylation, and 1p19q codeletion in gliomas were associated with more favorable prognoses." (PMID 33240891, 2020). "Frontal lobe involvement, oligodendroglial histology, lower Ki67 expression, WHO grades II and III gliomas, and methylated O6-methylguanine-DNA methyltransferase (MGMT) promoters were significantly associated with the presence of IDH1 mutations." (PMID 32856857, 2020). "Focusing on post-TMZ recurrent gliomas that have MGMT promoter methylation and/or IDH1 mutations increases the per-case value of such screening." (PMID 32051040, 2020). "For example, normal human astrocytes, when stimulated by glioma cells, increase the EV levels of MGMT mRNA, encoding the O6-alkylguanine DNA alkyltransferase." (PMID 33569385, 2020). "Our study demonstrated that TERT promoter mutations showed contradicting effects in MGMT-meth and MGMT-unmeth gliomas." (PMID 32957941, 2020). "While TERT promoter mutation showed a poor survival prognosis in glioma patients, O6-methylguanine-DNA methyltransferase (MGMT) methylation has long been recognized as an important factor in treatment decisions, and is also a positive prognostic factor." (PMID 32957941, 2020). "The association of MGMT promotor methylation and favourable outcome is less well established in glioma WHO grade II." (PMID 33184319, 2020). "This prospective clinical trial investigated sodium (23Na) MRI at 7 Tesla (T) field strength as biomarker for tumor extent, isocitrate dehydrogenase (IDH) mutation and O6-methylguanine DNA methyltransferase (MGMT) promotor methylation in glioma patients." (PMID 33002860, 2020). "TOX was up-regulated in MGMT promotor methylated glioma, glioma with IDH mutation, and glioma with 1p/19q codeletion." (PMID 32762688, 2020). "The implications of molecular biomarkers IDH1/2 mutations and MGMT gene promoter methylation were evaluated for prognostic outcome of glioma patients." (PMID 33552543, 2020). "Patients with the IDH mutation have a better prognosis than those without IDH mutation and drug temozolomide, used for glioma treatment, significantly prolonged survival of patients with hypermethylation of the MGMT gene promoter." (PMID 33036421, 2020). "The IDH mutation status, 1p/19q co-deletion status, and MGMT promoter status play important roles in the prognosis and chemotherapy outcomes of glioma patients and vary significantly among glioma patients." (PMID 33329553, 2020).
glioma (continued). "IDH1/2 mutations proved as independent prognostic factors in glioma and correlated with MGMT methylation for better survival." (PMID 33552543, 2020). "In MGMT-methylated (MGMT-meth) gliomas, the presence of the TERT promoter mutation was associated with an improved OS (HR = 0.73; 95% CI = 0.55–0.98; p-value = 0.04)." (PMID 32957941, 2020). "Collectively, extent of MGMT promotor methylation in glioma WHO grade II depends on IDH mutation and on 1p19q co-deletion." (PMID 33184319, 2020). "Perioperative monitoring of anti‐MGMT‐02 peptide autoantibody levels was useful for identifying patients with glioma at poor prognosis and a high risk of tumor recurrence and poor prognosis." (PMID 31210005, 2019). "In peadiatric, as in adult gliomas, overexpression of MGMT is strongly associated with adverse outcome in children treated with alkylator-based chemotherapy independent of other clinical prognostic factors." (PMID 35582280, 2019). "We found that the seropositivity of MGMT‐02 peptide autoantibody in glioma patient serum was associated with shorter recurrence‐free survival compared with the seronegative patients." (PMID 31210005, 2019). "Then, we also analyzed the impact of TERT promoter mutations, PTEN deletion, EGFR amplification and MGMT promoter methylation in diagnosis, prognosis and response to therapy in glioma molecular subgroup." (PMID 31623593, 2019). "Following the reclassification of gliomas according to the 2016 WHO classification, we investigated the role of TERT promoter mutations, EGFR amplification, PTEN deletion and MGMT promoter methylation in molecular glioma subgroups." (PMID 31623593, 2019). "For chemotherapy, we found our risk score significantly associated with the methylation status of the MGMT promoter, which can effectively predict the responsiveness of glioma to alkylating agents, the commonly used chemotherapeutic drugs for glioma." (PMID 31803233, 2019). "Epigenetic inactivation of MGMT is linked to an enhanced response to chemotherapy-alkylating agents and increased OS in gliomas." (PMID 31428936, 2019). "Today, some glioma-specific molecular biomarkers include IDH mutations (grades II, III gliomas), chromosomal region 1p19q deletion, and MGMT promoter methylation." (PMID 31296788, 2019). "Classically, in glioma clinical trials, the most common biomarkers are the status of MGMT promoter methylation and IDH mutation but on the horizon are radiomic markers which can predict the treatment response to a particular treatment." (PMID 31475111, 2019). "As is known to all, IDH1/2 mutation and MGMT promoter methylation are two important biomarkers in glioma." (PMID 31379707, 2019). "Among these molecular markers, IDH1, 1p19q, and MGMT methylation are closely associated with the prognosis and chemotherapy sensitivity of glioma patients." (PMID 30995921, 2019). "In summary, the T/T genotype of MGMT rs12917 is likely to be linked to an enhanced susceptibility to cancer overall, especially glioma, in the Caucasian population." (PMID 30232235, 2018). "We found the reproducible predictive power of MGMT gene parameters to quantify its ability as cancer hallmark for its molecular and expression phenotypes of malignant glioma cells." (PMID 29712977, 2018). "Multivariate Cox regression analysis showed both MGMT methylation and loss of protein as significant independent prognostic factors in glioma patients with respect to lower Hazard Ratio (HR) for better OS and PFS) [p < 0.05]." (PMID 29712977, 2018). "High-risk low-grade gliomas are currently treated with temozolomide and radiotherapy; for these patients, MGMT promoter methylation represents an independent prognostic factor: particularly, unmethylated MGMT promoter is associated with worse prognosis." (PMID 30279357, 2018). "It has recently been documented that MGMT expression is associated with SP1 expression in glioma cell lines." (PMID 30583528, 2018).
glioma (continued). "Promoter hypermethylation of the repair gene that encodes MGMT is by far the most frequent epigenetic alteration in glioma." (PMID 28346397, 2017). "MGMT, encoding the extensively studied DNA-repair enzyme O6-methyl-guanine-DNA methyltransferase, is frequently inactivated in gliomas by promoter methylation, and this is an important marker for therapy response." (PMID 29089486, 2017). "It was demonstrated as an independent prognostic indicator, and showed interrelationships with known molecular marks such as MGMT promoter methylation status, and glioma CpG island methylator phenotype (G-CIMP) or IDH1 mutations." (PMID 29163774, 2017). "The methylation status of O-6-methylguanine-DNA methyltransferase (MGMT) is associated with the prognosis in gliomas and in other cancers." (PMID 28575062, 2017). "In the presented study, we analyzed the MGMT methylation levels in 83 glioma patients with a known IDH1 mutation status and re-evaluated the clinical data with two years extended novel observations." (PMID 27834917, 2016). "Many studies have shown that a deficiency of MGMT can increase the sensitivity of high grade glioma to alkylating agents." (PMID 27384876, 2016). "Using Spearman correlation analysis, we examined the association between endogenous miR-29c and Sp1, MGMT immunostaining intensity in human glioma tissues." (PMID 27384876, 2016). "The IDH1/2 mutations, 1p/19q status and MGMT promoter methylation are commonly recognized biomarkers in patients with gliomas." (PMID 27834917, 2016). "The IDH1/2 gene mutations, ATRX loss/mutation, 1p/19q status, and MGMT promoter methylation are increasingly used as prognostic or predictive biomarkers of gliomas." (PMID 27834917, 2016). "The DNA repair protein O6-methylguanine-DNA methyltransferase (MGMT) causes resistance of cancer cells to alkylating agents and, therefore, is a well-established predictive marker for high-grade gliomas that are routinely treated with alkylating drugs." (PMID 27158275, 2016). "Since CpG island hypermethylation of MGMT is the major cause of loss of its expression in gliomas, MGMT methylated glioma patients are more sensitive to alkylating agents." (PMID 26967246, 2016). "Meanwhile, it was found that MGMT promoter methylation is a predictive marker for benefit from alkylating agents only in high-grade glioma patients with IDH1 wildtype, but 1p/19q loss in high-grade glioma patients with IDH1 mutant." (PMID 27733166, 2016). "Increasing evidences have demonstrated that IDH1 mutations and MGMT methylation are associated with survival benefit in gliomas." (PMID 26556853, 2016). "In contrast, in a prospective study collecting longitudinal plasma samples from grade II–IV glioma patients, presence of methylated MGMT was associated with increased PFS and OS." (PMID 25720744, 2015). "The acquired methylation at the MGMT promoter results in silencing of the gene, which has been associated with prolonged survival in glioma patients, due to the enhanced susceptibility of tumor cells to the chemotherapeutic agents such as temozolomide." (PMID 26451167, 2015). "Pathway-specific gene-expression profiling to search for regulators of MGMT expression showed gene-expression signatures that associated with Wnt signalling in colon cancer, neuroblastoma, glioma, as well as for the Wnt-driven medulloblastoma subgroup." (PMID 26603103, 2015). "The loss of MGMT protein expression caused by hypermethylation of the MGMT promoter reduces the DNA repair activity of glioma cells, overcoming their resistance to alkylating agents." (PMID 26347581, 2015).
glioma (continued). "Recent clinical studies showed that methylation of MGMT is a useful predictor of the responsiveness of tumors to alkylating agents in gliomas, and is associated with good survival in patients treated with multidrug regimens." (PMID 25638164, 2015). "Only IDH mutation status (prognostic) and MGMT methylation status and 1p/19q co-deletion (predictive) are currently routinely used for evaluation of glioma patients by clinicians in the US and UK." (PMID 24716189, 2014). "In recent years, TMZ monotherapy has been attempted for elderly GB or low-grade glioma patients, and an association between the treatment response and the MGMT methylation status has been examined." (PMID 25175833, 2014). "The findings support reports that IDH1/2 mutations and MGMT methylation can be used in addition to tumour grade and clinical factors to predict survival in patients with recurrent high grade gliomas when treated with any of the therapy regimes used." (PMID 24952577, 2014). "Another SNP, rs12917 in the MGMT gene, was associated with decreased glioma risk by recessive model analysis (OR, 0.73; 95% CI, 0.54-0.98; P = 0.036)." (PMID 23683922, 2013). "In conclusion, we show here that both epigenetic (promoter methylation) and genetic (monosomy, locus deletion) alterations affecting MGMT are associated with lower MGMT mRNA levels in high-grade gliomas." (PMID 23505468, 2013). "To date, the strongest evidence that epigenetic alterations are associated with patient survival is provided by the methylation-associated silencing of the MGMT gene in gliomas." (PMID 24202337, 2013). "Loss of MGMT protein expression is frequently associated with transcriptional silencing of the MGMT gene by methylation of its CpG island promoter in various neoplasia, as exemplified by 35–55% of gliomas." (PMID 23346075, 2012). "We propose that the NHA cell systems are useful for investigating the mechanisms underlying MGMT expression and for improving glioma therapies." (PMID 17547775, 2007). "The stochastic nature of this hypermethylation event is of particular interest, since variation in MGMT CpG island hypermethylation in gliomas is associated with clinical response to alkylating agents." (PMID 17878930, 2007). "Current available data generated from investigations in cell lines and tumor samples, suggest that resistance to temozolomide is significantly linked to MGMT-mediated DNA repair in high-grade gliomas, primitive neuroectodermal tumors, and ependymomas." (PMID 17140455, 2006). "Conversely, inactivation of MGMT by methylation of the promoter has been associated with clinical response of gliomas to alkylating agents." (PMID 14562026, 2003). "In this study, we explored Q-3-Dec as a multi-target agent, which concomitantly impairs NF-κB/STAT3-dependent survival signaling, mitochondrial function, and O6-Methylguanine-DNA Methyltransferase (MGMT) expression, a DNA repair enzyme closely associated with chemoresistance, in glioma cells." (PMID 41751862, 2026). "The integration of FTO expression into multivariable prognostic models, alongside established markers like IDH status and MGMT promoter methylation, could potentially enhance risk stratification and guide personalized treatment decisions for glioma patients." (PMID 40970086, 2025). "Thus, combined with IDH1/2 mutations, MGMT promoter methylation status serves as an important prognostic marker for gliomas treated with radiation and chemotherapy." (PMID 39859375, 2025). "Additionally, molecular diagnostic parameters-such as IDH mutation, MGMT promoter methylation, and 1p/19q codeletion-were unavailable for most patients, precluding integration with molecular glioma classification frameworks." (PMID 40791217, 2025). "Patients with glioma of subtype 1, which had a better survival outcome, exhibited lower pathological grades, smaller tumor volumes, and a higher proportion of cases with both MGMT promoter methylation and IDH mutation, consistent with previous research." (PMID 41188782, 2025).